SOD2 (superoxide dismutase 2)
Diseases named in the same sentence as SOD2 in open-access papers (continued):
Sharing a sentence is not in itself a finding about the gene and the disease.
Obesity (continued). "A significant effect of obesity was detected on gene expression of antioxidant enzymes superoxide dismutases 1, 2 and 3 (Sod1, Sod2 and Sod3), since there was a significant increase in their mRNA levels in ScWAT in obese animals." (PMID 39576482, 2025). "Catalase and SOD2 expressions in the placental tissue were significantly lower in the maternal obesity group compared to the maternal lean control (p < 0.0001 and p = 0.0011, respectively)." (PMID 39409195, 2024). "A gene ontology analysis showed some proteins related to obesity in the “extracellular exosome” term among differentially identified proteins in the gene ontology cellular component terms Prelp, Sec13, and Sod2." (PMID 36674516, 2023). "This anti-obesity effect of SOD2 deletion in adipocytes was attributed to the activation of mitochondrial biogenesis and the promotion of mitochondrial fatty acid oxidation." (PMID 37627590, 2023). "The selected proteins Prelp, Sec13, and Sod2 identified by the proteomic analysis were chosen for their relevant role in obesity and different abundance between groups." (PMID 36674516, 2023). "A previous study that focused on the presence of Sod2 in saliva showed a greater total amount of Sod2 in subjects with obesity than in healthy controls." (PMID 36674516, 2023). "Previous studies on genetic variation of SOD2 have mainly focused on obesity, T2D, NASH and even fibrosis." (PMID 36330440, 2022). "Four SNPs were associated with higher obesity risk under heterozygote and dominant models for GSTM1 rs1056806 (C/T), homozygote model for SOD2 rs4880 (A/G), and homozygote and recessive models for GPX1 rs1800668 (A/G)." (PMID 33924357, 2021). "The anti-obesity effect of SOD2 deletion in adipocytes was attributed to an activated mitochondrial biogenesis and enhanced mitochondrial fatty acid oxidation." (PMID 33748199, 2021). "LF-CQPC07 upregulated the mRNA expression of SOD1, GSH-Px, SOD2, CAT, and GSH1 to increase the body’s antioxidant capacity and inhibit oxidative stress, thereby relieving liver damage and inflammation caused by obesity." (PMID 33531053, 2021). "SOD2 rs4880 had higher odds of developing obesity under homozygote comparison model (G/G vs. A/A: OR = 1.97, 95%CI = 1.0–3.86, p = 0.045)." (PMID 33924357, 2021). "Interactome network analysis of the lower expressed genes in FTO obesity-risk genotype suggests that under normal conditions, DECR1 (dienoyl-CoA reductase), LIPE, LDHB, SOD2, ATP5B, and J are central elements in maintaining connectivity." (PMID 32316277, 2020). "As UCPs affect the process of insulin secretion in response to actual glycemia, maintaining proper SOD2 activity is important in context of obesity." (PMID 32709094, 2020). "Adipocyte-targeted Sod2 knockout mice prevent HFD-induced obesity and IR via increasing in mitochondrial biogenesis and fatty acid oxidation, leading to the clearance of circulating FFA and the improvement of IR." (PMID 31396447, 2019). "In particular, modulation of SOD2 has been observed in adipose tissue of obese patients, possibly to mitigate mitochondrial dysfunction correlated with the pathophysiology of obesity." (PMID 27399681, 2016). "Our data evidence that sTAC and TBARS are associated with obesity, showing a negative relationship in Mexican children who are non-carriers of SOD2 rs4880 and GPX1 rs1050450." (PMID 40867795, 2025). "Moreover, our study reveals that the activity of mitochondrial SOD2 is even more suppressed by HFD/obesity." (PMID 39230054, 2024). "Consistent with previous reports, at the molecular level, diet-induced obesity caused a decrease in antioxidant enzyme (SOD2 and catalase) mRNA expression without any change in pro-oxidant (NOX2) mRNA expression in murine aortas." (PMID 35073378, 2022). "The expression of SOD2 is higher in patients with obesity than in healthy individuals." (PMID 35328013, 2022).
Obesity (continued). "However, mice with an adipocyte-selective knockout of SOD2, the isoform in mitochondrial matrix, exhibited resistance to obesity induced by high-fat diet and enhanced energy expenditure." (PMID 33748199, 2021). "Interestingly, adipocyte-targeted “SOD2 knockout mice” has prevented high-fat-diet-induced obesity and insulin resistance, supporting the present findings." (PMID 33924357, 2021). "Similarly, reduction in ROS production and increase in SOD2 expression, an endogenous antioxidant defense that is significantly decreased in obesity, after TR treatment, are in line with the antioxidant activities of the enzymes present in EVOO." (PMID 33376578, 2020). "SOD2, found mainly in the mitochondria, by neutralizing superoxide anion, prevents from increased activation of uncoupling proteins (UCPs) by superoxide anion (which is observed in state of chronic hyperglycemia, as found in obesity)." (PMID 32709094, 2020). "Our results show that the Sod2 protein was significantly more abundant in the obese group compared to the control group, probably due to the increase in the number of superoxide anions, suggesting a preventive role of Sod2 in inflammation progression that occurred as a result of obesity." (PMID 36674516, 2023). "We aimed to assess the direct and modulatory effects of SNPs in antioxidant genes (SOD2 rs4880, GPX1 rs1050450, GPX7 rs835337, CAT rs1001179) on the relationships among obesity-related oxidative stress markers in Mexican children." (PMID 40867795, 2025). "In the present study, we investigated the direct and modulatory effects of four antioxidant enzyme SNPs (SOD2 rs4880, GPX1 rs1050450, GPX7 rs835337, and CAT rs1001179) on the relationships among obesity-related oxidative stress markers in Mexican children." (PMID 40867795, 2025). "Based on these results, 1) WTD-induced obesity downregulates the catalase mRNA; and 2) the combination of repeated GSs and diet-induced obesity synergistically upregulates the NOX2 and p47phox mRNAs and downregulates the SOD2 mRNA." (PMID 35073378, 2022). "Interestingly, the activity of the mitochondrial SOD2 isozyme coded by this gene has been underscored in neutralizing the mitochondrial O2•−, preventing the uncoupler proteins hyperactivity that is induced by this reactive oxygen species in the context of obesity." (PMID 33924357, 2021). "Obesity was positively correlated with GSTM1 (r = 0.109, p = 0.035) and SOD2 (r = 0.121, p = 0.046)." (PMID 33924357, 2021). "Inheritance association models revealed that four SNPs to have a prediction value for developing obesity, namely GSTM1 rs1056806 (C/T), SOD2 rs4880 (A/G), SOD3 rs2536512 (A/G), and GPX1 rs1800668 (A/G)." (PMID 33924357, 2021). "Under metabolic derangement, higher SOD2 isozyme activity might induce higher mitochondrial hydrogen peroxide (H2O2) accumulation associated with oxidative-stress-related insulin resistance, dyslipidemia, and unbalanced energy homeostasis, which characterize the obesity state." (PMID 33924357, 2021). "This study is a first step towards the identification of biomarkers for early-stage obesity (GSTT1, GSTT3, GSTM1, MGST1, MGST3, SOD2, CAT) and glucose load (CRYM) in cattle." (PMID 30235219, 2018). "The expression of antioxidant enzymes, including catalase, superoxide dismutase I (SOD1), and superoxide dismutase II (SOD2), in the aorta was not significantly affected by obesity and pioglitazone treatment." (PMID 33781257, 2021). "An increase in SOD2 activity was coexistent with obesity in men, and exposition to cigarette smoke in non-obese individuals." (PMID 32709094, 2020). "Neither Nrf2 nor Keap1 was affected by maternal obesity or grape juice intake, and antioxidant genes Ogg1, Ogg2, Sod1 or Sod2 were not affected either." (PMID 32731460, 2020). "In addition, the HFD/fucoidan-fed obese gerbils showed significant increase in the obesity-mediated decreases of levels of SOD1 and SOD2 in the pre- and post-ischemic phases." (PMID 30696078, 2019).
Obesity (continued). "Therefore, the present study aims to investigate both the direct and modulatory effects of four SNPs in antioxidant genes (SOD2 rs4880, GPX1 rs1050450, GPX7 rs835337, CAT rs1001179) on the relationships among obesity-related oxidative stress markers in Mexican children." (PMID 40867795, 2025). "However, abundance of antioxidant enzymes such as SOD1 and SOD2, and electron transport chain complexes in skeletal muscle were not affected by obesity or dietary supplements." (PMID 38886475, 2024). "Moreover, except for NOX4 expression, which trended lower, NFE2L2, NQO1, SOD2, and CAT gene expression declined in patients with obesity (BMI = 47–74) with NASH and fibrosis (NAS = 5–6; fibrosis score = 1–2) to levels evident in patients with obesity with nonsteatotic livers." (PMID 38060313, 2023). "Moreover, STAT3, MCL1, PMAIP1, SOD2, FOXO3, FOS, FKBP5 may play an essential role in the genesis and growth of obesity and might serve as a possible therapeutic target." (PMID 34712134, 2021). "Zhou and colleagues investigated the effects of prenatal PM exposure on superoxide dismutase 2 (SOD2) methylation, as it is responsible for detoxifying superoxide radicals, preventing oxidative injury that leads to many diseases, such as tumors, obesity, and cardiovascular and neurological diseases." (PMID 31470889, 2019). "The identification of SOD2 rs4880 AA or GPX1 rs1050450 GA + AA carriers may support targeted interventions based on diet and physical activity to promote the non-enzymatic antioxidant response and contribute to mitigating oxidative stress and preventing metabolic complications related to obesity." (PMID 40867795, 2025). "Therefore, NAFL, but not obesity per se, was accompanied by the increased expression of NFE2L2 targets genes, including NOX4, which encodes a ROS-producing enzyme, and NQO1, SOD2, and CAT, which encode key antioxidant defense enzymes, but these declined with more advanced disease and fibrosis." (PMID 38060313, 2023). "In our experimental model we have not detected modulation in SOD-2 or Catalase protein levels, therefore CR preserves the antioxidant enzymes proteins levels and probably through the modulation of their activity levels it counteracts the oxidative damage resulting from aging and obesity." (PMID 37760081, 2023).
Hypertension (62 papers, 2007 to 2026). The presence of chronic increased pressure in the systemic arterial system. "The loss of SIRT3 leads to increased SOD2 acetylation, causing severe oxidative stress, hypertension, and endothelial dysfunction." (PMID 39458930, 2024). "SIRT3 depletion causes hyperacetylation of mitochondrial SOD2 and overproduction of oxidative stress, which results in endothelial dysfunction, vascular inflammation, and hypertension in mice." (PMID 37143582, 2023). "More recent studies suggested that hypertension caused oxidative damage in mitochondria in endothelial cells via SIRT3/superoxide dismutase 2 (SOD2)." (PMID 33557283, 2021). "The mixture of RSV/QSC reversed hypertension caused by short- and long-term exposure to sucrose by modifying the expression of eNOS, the antioxidant capacity, and the expression of SOD2, and increased the expression of SIRT1 in the aortas of MS rats." (PMID 32210194, 2020). "Previous data from other labs as well as ours have shown that SIRT3 deficiency and resultant SOD2 hyperacetylation and mitochondrial ROS overproduction contribute to the development of hypertension and vascular dysfunction in obesity." (PMID 32015327, 2020). "Perhaps the most immediate question would be the potential impact of this allelic variation of SOD2 upon susceptibility to hypertension among African-Americans." (PMID 17331249, 2007). "Third, while susceptibility to hypertension is clearly modulated by multiple genetic loci, a region of chromosome 6 that encompasses the SOD2 locus is among those that have been implicated." (PMID 17331249, 2007). "Given the recent evidence that SOD2 is in a region on chromosome 6 linked to susceptibility to hypertension, it will be of interest to investigate possible associations of this polymorphism with cardiovascular disorders." (PMID 17331249, 2007). "In conclusion, the reduced total antioxidant capacity and expression of SOD2 might participate as part of the mechanisms that underlie hypertension in both models." (PMID 29882756, 2018). "We found no changes in SOD1 in the short or long- term exposure to sucrose; however, SOD2 was decreased in both conditions and could participate in the underlying causes of sucrose-induced hypertension." (PMID 29882756, 2018). "Furthermore, our original findings indicate that RPO related attenuation of hypertension-induced abnormalities in myocardial SOD2 and NOS were associated with the protection of heart function during post-ischemic reperfusion." (PMID 29160855, 2017). "In a mouse model of angiotensin II‐induced hypertension, it was shown that aortic SOD2 acetylation had an inverse correlation with aortic SOD2 activity and a direct correlation with hypertension severity." (PMID 40511632, 2025). "In our study, we found a significant increase in plasma SOD1 and erythrocyte SOD2 levels proportionally with a rise in MDA in patients with T2DM or hypertension or their combination versus the healthy group." (PMID 39273236, 2024). "SOD2 inactivation increased mitochondrial O2-• and declined endothelial nitric oxide and was related to hypertension." (PMID 37956134, 2023). "Ecklonia cava extract (ECE) decreases hypertension-related vascular calcification through SOD2 SIRT3-deacetylation." (PMID 37237500, 2023). "In RVLM, transcriptional upregulation of sod2 protects against mitochondrial oxidative stress and hypertension in Ang II treatment in normotensive rats." (PMID 36140333, 2022). "One study found that diminished Sirt3 expression significantly increased mtROS production due to SOD2 acetylation, which promotes the development of hypertension." (PMID 35769207, 2022). "SOD2 also participates in the protection again hypertension and cardiovascular complications conferred by the mitochondria-target antioxidants." (PMID 36140333, 2022).
Hypertension (continued). "Mitochondrial oxidative stress–induced endothelial dysfunction in hypertension has been attributed to reduced sirtuin 3 (SIRT3)–mediated superoxide dismutase 2 (SOD2) signalling." (PMID 32389339, 2020). "Changes in SOD2 expression and Sirt3 were also present in adult rats that developed hypertension after having ingested sucrose during the critical window." (PMID 30717220, 2019). "We also studied the expression of Sirt1, which regulates eNOS expression and Sirt3, which regulates SOD2 expression as possible epigenetic targets of enzyme expression involved in the long- term programming of hypertension." (PMID 30717220, 2019). "On the other hand, overexpression of SOD2 decreased mitochondrial superoxide and restored NO bioavailability in hypertension." (PMID 29160855, 2017). "We demonstrated the importance of the activation of AMPK abolished the Rac1-modulated increase in NADPH oxidase activity and decreases in SOD2 activities in the RVLM during fructose-induced hypertension." (PMID 27138844, 2016). "Besides, SIRT3 depletion can induce mitochondrial damage due to SOD2 acetylation and SOD2 inactivation in vascular dysfunction and hypertension." (PMID 39300372, 2024). "Moreover, SOD2 activity is regulated by acetylation, mostly on the lysine 68 (K68) site, contributing to SOD2 inactivation and to hypertension." (PMID 35453408, 2022). "Besides, the expression of SOD2 significantly changed in the hypertension-induced cardiac dysfunction." (PMID 34803698, 2021). "There are also epigenetic factors that can influence the appearance of hypertension in adults, such as hypermethylation of genes, including superoxide dismutase-2 (SOD2) or Granulysin, or increased levels of histone acetylation at the promoter of the endothelial oxide synthetase gene (eNOS)." (PMID 31649728, 2019). "Moreover, when other antioxidant-related gene polymorphisms (SOD2, SOD3, PON1, and GSTT1) are present, GPX3 rs3828599 is more strongly associated with the incidence of hypertension and is positively associated with coronary artery disease and with the severity of coronary atherosclerosis." (PMID 41152890, 2025). "Moreover, SIRT3, an important regulator of mitochondrial antioxidant defense mechanism, scavenged mitoROS by stimulating deacetylation of superoxide dismutase 2, thus improving mitochondrial oxidative stress damage including essential hypertension, cardiac fibrosis, and diabetic cardiomyopathy." (PMID 36192726, 2022). "In the CS-induced hypertension mouse model, the expression of SIRT3 was reduced, as was the hyperacetylation of superoxide dismutase 2, and superoxide dismutase 2 activity was inhibited, which promoted mitochondrial oxidative stress." (PMID 31711545, 2019). "In animal models of hypertension, cardiac disease and ischemic stroke, Sirt3 has shown to suppress oxidative stress by regulating NOX2, NOX4, SOD2, Nrf2 and FoxO3a." (PMID 30362958, 2018). "In a pharmacological rat model of hypertension (L-NAME induced hypertension) SOD-2 was induced in the LV but not in the RV." (PMID 30618811, 2018). "However, SOD1 and SOD2 concentrations in the SAP and ACS subjects with hypertension were elevated as compared with control." (PMID 27830142, 2016). "Interestingly, our data showed that after the treatment, there was a significant increase in the SOD-2 expression in the OVX-PHE group, enzyme that promotes O2•− dismutation, which is formed in greater amounts in hypertension." (PMID 28101057, 2016). "Lead-induced hypertension in rats resulted in the upregulation of the gp91phox subunit of NAD(P)H oxidase in the left ventricle and the brain and compensatory upregulation of superoxide dismutase, Mn-SOD (SOD2) in the heart and Cu,Zn-SOD (SOD1) in the brain and kidney." (PMID 39567405, 2025).